OR52K2 (olfactory receptor family 52 subfamily K member 2)
Description:
Odorant receptor.
Synonyms: OR11-7
Tractability: Antibody: UniProt places it where antibodies can reach, with medium confidence; UniProt predicts a signal peptide or a membrane-spanning region; its Gene Ontology location is reachable by antibodies, with medium confidence.
Gene: Protein-coding gene on chromosome 11 (4,449,295 to 4,450,361, forward strand). Ensembl gene ENSG00000181963.
Subcellular location: Cell membrane
Pathways (Reactome):
Sensory Perception: Expression and translocation of olfactory receptors
Gene Ontology:
Molecular function: olfactory receptor activity; G protein-coupled receptor activity
Biological process: detection of chemical stimulus involved in sensory perception of smell; G protein-coupled receptor signaling pathway; nervous system process
Cellular component: plasma membrane; membrane
Genetic constraint (gnomAD): Loss-of-function variants: 11 observed, 12.82 expected, observed/expected ratio (o/e) 0.86, 90% interval 0.54 to 1.42. The synonymous counts are far from expectation, so gnomAD's model fits this gene poorly and the ratio says little. Missense variants: 465 observed, 403.47 expected, observed/expected ratio (o/e) 1.15, 90% interval 1.07 to 1.24. Synonymous variants: 199 observed, 154.57 expected, observed/expected ratio (o/e) 1.29, 90% interval 1.15 to 1.45.
Homologues: Orthologues: chimpanzee OR52K2 (98% identical), pig OR52K2 (90% identical), guinea pig OR52K2 (89% identical), mouse Or52k2 (88% identical), rat Or52k2 (88% identical). Paralogues in human: OR52K1 (91% identical), OR52E8 (53% identical), OR52L1 (52% identical), OR51G2 (51% identical), OR52E6 (51% identical), OR52D1 (51% identical), OR52J3 (51% identical), OR52N4 (50% identical), OR52B6 (50% identical), OR52B2 (49% identical), OR51E1 (49% identical), OR51G1 (49% identical), and 39 more.
Diseases named in the same sentence as OR52K2 in open-access papers:
OR52K2 is named in the same sentence as 1 disease in open-access papers, as found by Europe PMC text mining. Sharing a sentence is not in itself a finding about the gene and the disease. The quoted sentences say what the papers report.
bacterial meningitis (1 paper, 2024). Inflammation of the membranes surrounding the brain and spinal cord due to a bacterial infection. "The diagnostic value of GPR68, KIF5C OR52K2, and CCR5 were assessed in bacterial meningitis." (PMID 38347610, 2024). "Moreover, KIF5C, GPR68, and OR52K2, with higher AUC, may be potential diagnosis makers in bacterial meningitis." (PMID 38347610, 2024). "In bacterial meningitis patients, 8 co-expression relationships were constructed between 8 mRNAs (ACBD7, OR52K2, GPR68, SHISA4, KIF5C, OR52P2P, OR51R1P, and CCR5) and 1 lncRNA." (PMID 38347610, 2024). "In this study, CCR5, KIF5C, OR52P2P, OR52K2, and OR51R1P were co-expression with lncRNA AC091138.1 in bacterial meningitis specific co-expression networks." (PMID 38347610, 2024).